MRPS27 (mitochondrial ribosomal protein S27)
Description:
RNA-binding component of the mitochondrial small ribosomal subunit (mt-SSU) that plays a role in mitochondrial protein synthesis. Stimulates mitochondrial mRNA translation of subunit components of the mitochondrial electron transport chain. Binds to the mitochondrial 12S rRNA (12S mt-rRNA) and tRNA(Glu). Involved also in positive regulation of cell proliferation and tumor cell growth.
Synonyms: MRP-S27; S27mt; KIAA0264; mS27
Tractability: Small molecule: a structure with a bound ligand is known. PROTAC: ubiquitination databases record sites on it; its protein half-life has been measured.
Target class: Other cytosolic protein
Gene: Protein-coding gene on chromosome 5 (72,214,953 to 72,321,717, reverse strand). Ensembl gene ENSG00000113048.
Subcellular location: Cytoplasm; Mitochondrion
Subcellular location (Human Protein Atlas): Mitochondria; Nucleoli
Pathways (Reactome):
Metabolism of proteins: Mitochondrial ribosome-associated quality control; Mitochondrial translation elongation; Mitochondrial translation initiation; Mitochondrial translation termination
Gene Ontology:
Molecular function: protein binding; rRNA binding; tRNA binding
Biological process: cell population proliferation; mitochondrial translation
Cellular component: cytoplasm; mitochondrial small ribosomal subunit; mitochondrion; mitochondrial inner membrane
Genetic constraint (gnomAD): Loss-of-function variants: 23 observed, 28.34 expected, observed/expected ratio (o/e) 0.81, 90% interval 0.58 to 1.15. The upper end of that interval is the gene's LOEUF score, 1.15, which puts it in group 5 of 6, group 1 being the genes least tolerant of losing a copy. Missense variants: 342 observed, 346.88 expected, observed/expected ratio (o/e) 0.99, 90% interval 0.9 to 1.08. Synonymous variants: 140 observed, 136.61 expected, observed/expected ratio (o/e) 1.02, 90% interval 0.89 to 1.18.
Homologues: Orthologues: chimpanzee MRPS27 (99% identical), macaque MRPS27 (94% identical), guinea pig MRPS27 (83% identical), dog MRPS27 (82% identical), pig MRPS27 (82% identical), rat Mrps27 (77% identical), mouse Mrps27 (77% identical), rabbit MRPS27 (72% identical), tropical clawed frog mrps27 (58% identical), zebrafish mrps27 (50% identical), Caenorhabditis elegans mrps-27 (19% identical), Drosophila melanogaster CG4882 (16% identical).
Diseases named in the same sentence as MRPS27 in open-access papers:
MRPS27 is named in the same sentence as 11 diseases in open-access papers, as found by Europe PMC text mining. Sharing a sentence is not in itself a finding about the gene and the disease. The quoted sentences say what the papers report.
Alzheimer disease (1 paper, 2025). A progressive, neurodegenerative disease characterized by loss of function and death of nerve cells in several areas of the brain leading to loss of cognitive function such as memory and language. "Consequently, these two genes were excluded, leaving six critical genes with diagnostic significance for Alzheimer’s disease (AD): ACO2, CS, MRPS27, SDHA, SLC25A20, and SYNJ2BP." (PMID 39757625, 2025).
Ataxia (1 paper, 2022). Ataxia refers to impaired coordination of voluntary muscle movement. "Among the genes related to cerebellar volume in the four substructure GWASs we find genes related to ataxia (PEX7, MRPS27, PTK2), neurodevelopment (YPEL3, CASP6, TRIM11, GNB5) and microcephaly (PDCD6IP, USP28)." (PMID 35546225, 2022).
breast carcinoma (1 paper, 2024). "Pan-cancer analysis of the Human Protein Atlas (HPA) database revealed that among the various cancer types expressing MRPS27, breast cancer was the third-ranked cancer type with the majority (>90%) of patients appearing positive for MRPS27." (PMID 38617541, 2024). "Nevertheless, we show that MRPS27 is positively correlated with the stemness-related gene signature in breast cancer and MRPS27 knockdown induces nucleolar stress in TNBC." (PMID 38617541, 2024). "The correlation between MRPS27 and the stemness-related gene signature 45 was confirmed by GEPIA2 analysis in breast cancer patients." (PMID 38617541, 2024). "In addition, the protein level of MRPS27 was higher in breast cancer compared with normal tissues (data not shown)." (PMID 38617541, 2024).
emphysema (1 paper, 2022). "Moreover, we did not detect any significant changes in MRPS27 and MRPL48 levels using lung tissue obtained from nonsmokers, smokers, and emphysema patients by RT-PCR and Western blotting." (PMID 35884802, 2022). "Moreover, we found that MRPS27 mRNA levels were decreased in ATII cells in smokers and emphysema patients compared to nonsmokers." (PMID 35884802, 2022).
Flavivirus Infections (1 paper, 2023). Infections with viruses of the genus FLAVIVIRUS, family FLAVIVIRIDAE. "We next selected two of the most downregulated proteins in Flavivirus infections (previously identified in the SILAC experiment), HMGA1 and MRPS27, for validation by Western blot." (PMID 37515107, 2023).
lymphoma (1 paper, 2016). A malignant (clonal) proliferation of B- lymphocytes or T- lymphocytes which involves the lymph nodes, bone marrow and/or extranodal sites. "Knockdown of Ptcd3 or other mitochondrial ribosomal proteins (Mrps5 or Mrps27) decreased both expression of mitochondrion-encoded proteins and respiration rates, and was detrimental to Myc-driven lymphomas." (PMID 27635472, 2016).
cancer (3 papers, 2018 to 2024). A tumor composed of atypical neoplastic, often pleomorphic cells that invade other tissues. "To reveal the pathophysiological relevance of MRPS27 in TNBC, we performed bioinformatics and experimental analyses on the expression profile of MRPS27 in cancer tissues and cell lines." (PMID 38617541, 2024). "The expression levels of LIAS had a positive correlation with the expression levels of CTD-2366F13.1 (R = 0.47, p < 0.001), RAD17 (R = 0.48, p < 0.001), OCIAD1 (R = 0.49, p < 0.001), PACRGL (R = 0.49, p < 0.001), MRPS27 (R = 0.49, p < 0.001), and THAP9 (R = 0.49, p < 0.001) in pan-cancer." (PMID 35982953, 2022).
tumor (2 papers, 2016 to 2024). "Compared with those injected with shNC cells, the mice receiving MRPS27 knockdown cells had decreased tumor growth over a period of 6 weeks post injection and decreased tumor weight." (PMID 38617541, 2024). "We then used a mouse model of orthotopic tumor growth to evaluate the effect of MRPS27 knockdown in vivo." (PMID 38617541, 2024). "Mitochondrial ribosomal protein S27 (MRPS27), the top-ranked risky model gene, was highly expressed and correlated with tumor stage and lymph node involvement in TNBC." (PMID 38617541, 2024). "The TN clusters (TN and TN+Her2) include proliferative proteins (MCM3 and 5), translation related proteins (RCL1, MRPS27, EIF2S2 and EEF1G) and metabolic enzymes (glutaminase and hexokinase 2), which reflect the higher dependence on glutamine and glucose of TN versus the other tumours." (PMID 26725330, 2016).
MRPS27 also shares sentences with these, for which no sentence is quoted: microcephaly (1 paper); ovarian carcinoma (1); triple-negative breast carcinoma (1).